CFH (complement factor H)
Diseases named in the same sentence as CFH in open-access papers (continued):
Sharing a sentence is not in itself a finding about the gene and the disease.
systemic lupus erythematosus (16 papers, 2011 to 2025). An autoimmune multi-organ disease typically associated with vasculopathy and autoantibody production. "Low levels or functional changes in complement regulators like CFH—often due to genetic variants—have been linked to autoimmune and inflammatory diseases such as IgAN, systemic lupus erythematosus, and several kidney disorders." (PMID 40868541, 2025). "More studies, including the direct effects of anti-CFH autoantibodies on spontaneous or induced lupus model with CFH deficiency, are needed." (PMID 37322353, 2023). "A recent study has shown that CFH deficiency accelerates the development of lupus nephritis in lupus-prone mice MRL-lpr." (PMID 21637784, 2011). "For instance, lupus-prone mice deficient in CFH exhibit unregulated cAP activation, hypocomplementemia, severe proteinuria, accelerated kidney failure, and early mortality compared to CFH-intact counterparts." (PMID 41019087, 2025). "SERPING1, C3, FGA, FGG, and CFH were significantly related to autoimmune diseases, and C3 in particular is associated with systemic lupus erythematosus (SLE) that shows a similar immunopathogenic basis to pSS." (PMID 34516718, 2021). "Genetic variants in CFH and CFH-related proteins (CFHRs) have been associated with systemic lupus erythematosus (SLE) development." (PMID 31354740, 2019). "Herein, we aimed to explore the roles of anti-CFH autoantibodies based on pristane-induced lupus mice." (PMID 37322353, 2023). "We used a pristane-induced lupus mice model to assess the effects of anti-CFH autoantibodies in vivo." (PMID 37322353, 2023). "Anti-complement factor H (CFH) autoantibodies could be detected in lupus and its significance remained to be elucidated." (PMID 37322353, 2023). "Especially, the correlation analysis in pristane-induced lupus mice group further supported the negative association between anti-CFH antibodies and lupus disease activity." (PMID 37322353, 2023). "The absence of an association of CFHR3-1Δ with renal disorder in lupus suggests that CFHR3 and CFHR1 play a different role from CFH in the pathogenesis of lupus, although further studies are required to validate the lack of association between the CFHR3-1Δ deletion and renal disorder in SLE." (PMID 21637784, 2011). "Thus, we thought that the subsequent developed anti-CFH autoantibodies might play the long term protective role in the chronic disease process of pristane-induced lupus mice other than the injection of hCFH." (PMID 37322353, 2023). "Mutations of complement regulatory proteins including membrane cofactor protein, complement factor I, and complement factor H have also been observed in patients with systemic lupus erythematosus (SLE) and antiphospholipid antibody positivity." (PMID 25474424, 2014). "C3, CFH, SERPING1, FGA, and FGG were significantly enriched in the “complex and coagulation cascades pathway,” C3 was also enriched in the “systemic lupus erythematosus” pathway, and PRB1 in the “salivary secretion” pathway." (PMID 34516718, 2021).
Hypertension (13 papers, 2008 to 2023). The presence of chronic increased pressure in the systemic arterial system. "Associations of CFH genetic variants genotypes with blood pressure and hypertension stratified by C-reactive protein levels." (PMID 22848687, 2012). "Previous studies have shown an association between CFH genetic polymorphism and hypertension, indicating that CFH may be a significant predictor of CVD." (PMID 35740418, 2022). "Taken together, our results suggest that common genetic variation in CFH and its related genes may contribute to variation in blood pressure and hypertension risk in Chinese Hans." (PMID 22848687, 2012). "Associations of CFH genetic variants with blood pressure and hypertension in Chinese Hans." (PMID 22848687, 2012). "In conclusion, our results suggest that genetic variations in CFH and its related genes may contribute to hypertension risk in Chinese Hans." (PMID 22848687, 2012). "Therefore, the rs7542235 (CFHR1–3Δ) may contribute to hypertension risk by increasing inflammatory response, and rs2274700 (A473A) is likely to be in LD with other genetic variants that affect expression of CFH or binding capacity of CFH with CRP." (PMID 22848687, 2012). "However, whether dysfunction or mutation of CFH and its related proteins is associated with hypertension is currently unknown." (PMID 22848687, 2012). "This possibility is in line with the report here of two cases of aHUS secondary to chronic severe hypertension in patients who carried SVs affecting the CFH or CFHRs genes, respectively." (PMID 36793547, 2022). "Partial remission was observed in 42% (n = 8), including 7 with arterial hypertension and 5 with detectable CFH-Abs." (PMID 33025207, 2021). "However, whether genetic changes of complement factor H (CFH) and its related genes are associated with hypertension is unknown." (PMID 22848687, 2012). "Still, an increased expression of SVEP1, NRP1, RNASE1, QSOX1, and GKN1, along with decreased expression of XYLT2, CFH, LEP, and CETP serum levels were found in patients with hypertension." (PMID 37792298, 2023). "Of these, 4,799 subjects have complete data on the following variables: early AMD, any AMD, gender, smoking, age, hypertension, diabetes, hyperlipidaemia, CKD, CFH rs10801555 and ARMS2 rs3750847." (PMID 25786237, 2015).
lupus nephritis (13 papers, 2013 to 2024). Glomerulonephritis in the context of systemic lupus erythematosus. "The deficiency of CFH results in an accelerated development of lupus nephritis in an animal model for SLE." (PMID 32922395, 2020). "Further, mCRP autoantibodies have been reported to play a pathogenic role in lupus nephritis by influencing the interaction between mCRP and C1q or complement factor H and regulating complement activation." (PMID 31296087, 2019). "Moreover, the genotype of CFH rs1061170 was found to be related to specific histopathologic subtypes of lupus nephritis, highlighting the relevance of complement polymorphisms in inflammatory disease." (PMID 31861421, 2019). "However, 35–47 and 199–206 are predominant epitopes in mCRP recognized by autoantibodies, with the former being critical for lupus nephritis; anti-35–47 mCRP IgG inhibit the interactions between mCRP and complement factor H and are associated with renal injury and the prognosis of the disease." (PMID 37873776, 2023). "It should be noticed that some differences existed in the bio-functions and immunologic features of the anti-CFH autoantibodies between lupus nephritis model and human aHUS and C3G, in which the latter presented with more pathogenic effects." (PMID 37322353, 2023). "In the current study, we explored the potential role of anti-CFH autoantibodies based on pristane-induced lupus nephritis." (PMID 37322353, 2023). "Our results suggested that anti-CFH autoantibodies could attenuate pristane-induced lupus nephritis by increasing bio-functions of CFH on regulating complement activation and controlling inflammation." (PMID 37322353, 2023). "Recently, we have demonstrated that mCRP may be protective in lupus nephritis by recruiting CFH, and autoantibodies against CBS abrogating this effect predicts worse prognosis." (PMID 29520264, 2018). "In summary, immunization with CFH and subsequent development of anti-CFH autoantibodies had significantly protective effects on murine lupus nephritis, which might be due to its increased bio-functions of CFH on regulating complement activation and controlling inflammation." (PMID 37322353, 2023). "Similarly, reduced binding of CFH to GAGs and CRP was found to be related to immune damage in SLE and lupus nephritis." (PMID 31861421, 2019). "Interestingly, anti-CFH autoantibodies could be also detected in patients with systemic lupus nephritis (SLE) and lupus nephritis (LN), and those autoantibodies may be protective in LN in vitro, although their roles in vivo remained to be further elucidated." (PMID 37322353, 2023). "In contrary to pervious study which analyzed the correlation of serum CFH and disease activity of patients with lupus nephritis, our study demonstrated that only serum CFI but not CFH and CD46 correlated statistically with SLEDAI scores." (PMID 29492211, 2018).
membranoproliferative glomerulonephritis (13 papers, 2008 to 2025). Inflammation of the glomeruli characterized by deposits at the intraglomerular mesangium, resulting in thickening of the glomerular basement membrane, activation of complement, and impaired kidney function secondary to damaged glomeruli. "In contrast, complete CFH knockout mice develop a different renal disease pattern, namely membranoproliferative glomerulonephritis." (PMID 28275964, 2018). "CFH knockout mice, which serve as a model for membranoproliferative glomerulonephritis, had significant changes in THP mRNA and protein concentrations." (PMID 28742158, 2017). "For example, studies of the RCA alpha block encompassing CFH and CFHR1-5 genes have shown associations with AMD, aHUS, Membranoproliferative Glomerulonephritis and SLE." (PMID 22558131, 2012). "On the other hand, complement factor H (Ctf) and prosaposin (Psap) are relatively downregulated in ROP-Os/+ kidneys, similar to observations in membranoproliferative glomerulonephritis (MPGN) and tubular damage." (PMID 22813067, 2012). "Additional support linking CFH to AMD comes from patients with membranoproliferative glomerulonephritis (MPGN) type II, a disease associated with CFH mutations, who develop drusen which are indistinguishable from those in AMD." (PMID 23825688, 2013). "The year 2007 saw publication of a report on a transgenic mouse model that spontaneously develops HUS, resulting from CFH knock out (CFH −/− mice develop membranoproliferative glomerulonephritis but not HUS) with knock in of a modified CFH that carries a deletion in SCR 16–20." (PMID 18594873, 2008).
meningococcal disease (13 papers, 2012 to 2023). "Based on this evidence, it is postulated that high plasma levels of CFH can increase the chance of Nm survival in the blood, consequently leading to an increased susceptibility to meningococcal infection." (PMID 29686800, 2018). "In meningococcal disease (referring to invasive Neisseria meningitidis brain or bloodstream infections), strong associations emerged between Factor H (CFH) and other CFH-related genes such as CFHR3 and CFHR1." (PMID 30405986, 2018). "Polymorphism of Complement Factor H (CFH) is associated with altered risk of invasive meningococcal disease (IMD)." (PMID 25798599, 2015). "Our study explored the characteristics of the association between meningococcal disease and CFH polymorphism, the relationship between fHBP subfamily and this association and the effects of other polymorphisms of complement system genes on disease risk." (PMID 25798599, 2015). "Genome-wide association studies have found variation within the complement factor H gene family links to host susceptibility to meningococcal disease caused by infection with Neisseria meningitidis." (PMID 25534642, 2014). "From the multiple discoveries of monogenic complement deficiencies to the associations of complement factor H and complement factor H-related three polymorphisms to meningococcal disease, the complement pathway is highlighted as being central to the genetic control of meningococcal disease." (PMID 32067109, 2020). "Similarly, a somewhat smaller GWAS in meningococcal disease confirmed an association with the complement factor H (CFH) gene, previously identified in a candidate gene study of this disease." (PMID 22312051, 2012). "fHbp binds human CFH, a negative regulator of the complement system, and has multiple roles during meningococcal infection." (PMID 36941192, 2023). "Recently it has been shown that variants in CFH and CFHR3 are associated with susceptibility to meningococcal disease." (PMID 23613724, 2013). "A genome-wide association study of 7,522 individuals in Europe identified single-nucleotide polymorphisms within genes encoding complement factor H (CFH) and CFH-related protein 3 (CFHR3), which were associated with host susceptibility to meningococcal disease." (PMID 30515161, 2018). "Indeed, SNPs in both CFH and CFHR3 are associated with altered susceptibility for meningococcal disease." (PMID 27007437, 2016). "We looked at several polymorphisms in complement factor H (CFH), a gene previously found to be associated with eye disease in published genome-wide association studies as well as host susceptibility to meningococcal disease." (PMID 25756647, 2015). "The functional basis for the relationship between CFH polymorphism and susceptibility to invasive meningococcal disease is not yet understood: It is likely that it relates to the interaction between CFH or CFH-related proteins and N. meningitidis." (PMID 25798599, 2015). "Studies of host susceptibility and bacterial genome-wide association studies (GWAS) highlight the importance of the interaction between fHbp and CFH and other complement factors, such as CFHR3, on the development of invasive meningococcal disease (IMD)." (PMID 36941192, 2023).
IgA nephropathy (12 papers, 2014 to 2026). "IgA nephropathy and the drusen in macular degeneration share genetic risk alleles in complement pathway genes CFH and CFHR1-540,41." (PMID 36316518, 2022). "Additionally, and most importantly, large genome-wide association studies (GWAS) of IgA nephropathy have consistently detected the susceptible locus 1q32, which contains the CFH and CFHRs genes." (PMID 38558821, 2024). "Genomic variants of CFH and their receptors were also shown to associate with IgA nephropathy." (PMID 24596580, 2014). "cFH is related to the severity and prognosis of IgA nephropathy." (PMID 33788378, 2021).
macular degeneration (12 papers, 2010 to 2023). Loss of vision in the central portion of the retina (macula), secondary to retinal degeneration. "CFH controls complement activation in the extracellular matrix and CFH risk variants are shared by drusen in macular degeneration and by SLE." (PMID 35497809, 2022). "The major risk allele for drusen in macular degeneration affects the alternative complement pathway regulator, CFH." (PMID 35817816, 2022). "In eight sporadic cases, we detected eight heterozygous rare sequence variants in six macular degeneration genes (CFH; FBLN1, OMIM 135820; FBLN3/EFEMP1, OMIM 601548; FBLN5, OMIM 604580; HMCN1, OMIM 608548; FBN2, OMIM 612570)." (PMID 27007659, 2016). "CFH encodes a protein that is secreted into the bloodstream and is essential for complement system regulation, and CFH polymorphisms are associated with macular degeneration." (PMID 21510904, 2011). "Interestingly, seven genes associated with macular degeneration (CFH, C3, C2, CFHR5, CFB and CFHR4, CFHR1) also form a statistically significant module in liver (p value < 10−26, z score = 10.85)." (PMID 27748412, 2016). "Similarly, the gene CFH has been associated with macular degeneration at least 19 times, as well as to the endo-phenotype of macular degeneration, choroidal neovascularization 3 times." (PMID 20092628, 2010). "To investigate possible binding targets for the disease risk domain SCR7 of CFH, we undertook a yeast 2-hybrid screen of expressed cDNAs from RPE/choroid from aged donors and identified a potential partner which also has associations with macular degeneration." (PMID 23840815, 2013). "Here, we optically examine retinal mitochondrial function as well as choroidal oxygenation and hemodynamics in aging C57 and complement factor H (CFH−/−) mice, proposed models of macular degeneration which suffer early retinal mitochondrial decline." (PMID 33558624, 2021). "Again, based on the interaction between PTX3 and complement factor H that contribute to maintain the retinal immunohomeostasis, the stimulation of PTX3 could reduce the pathophysiology of macular degeneration." (PMID 27559355, 2016). "Immunofluorescence (IF) was used to localize Fib3 and CFH in several donor eyes including normal eyes with no histological evidence of macular degeneration, and eyes with different forms of AMD." (PMID 23840815, 2013).
COVID-19 (11 papers, 2021 to 2024). A disease caused by infection with severe acute respiratory syndrome coronavirus 2. "In particular, a prospective cohort observational study identified several abnormal variants of complement factor H, C5b-9 (ADAMTS-13) in patients with COVID-19 who developed atypical hemolytic syndrome." (PMID 37626703, 2023). "In COVID-19, gene variants in the complement pathway, specifically CD59, CFH and C4BPa are associated with poorer outcomes and targeted studies have demonstrated elevations of C5a and C5b-9 in plasma from individuals with moderate and severe disease." (PMID 36330526, 2022). "COVID-19 might lead to its excessive plasma activation through the lectin pathway or as in severe Dengue virus infection through reducing complement factor H (FH) activity." (PMID 38234438, 2024). "In contrast, the patient in case 2 had a family history significant for HUS, normal ADAMTS13 activity and stool infectious studies, a high titer of anti-CFH autoantibody, and slow but excellent response to eculizumab, all of which favor a diagnosis of aHUS, with likely COVID-19 trigger." (PMID 34903272, 2021). "Moreover, we found an 2.5-fold increase of C9 in non-critical patients and a down-regulation of CFH; these findings suggest that, in critical COVID-19 patients, the C9 complement component might be impaired due to SARS-CoV-2 infection, as has already been shown for the hepatitis C virus." (PMID 33693030, 2021).
diabetes (11 papers, 2008 to 2021). "Our study design also included controlling for factors that could modify CRP expression as well as risk of AMD, including CFH genotype, smoking, body mass index (BMI), and diabetes, reducing the likelihood of observing false positive correlations." (PMID 18704199, 2008). "In age and sex adjusted Cox models, IL13 (HR = 0.78), EN-RAGE (1.30), CFH (1.24), IL18 (1.22) and CRP (1.32) were associated with incident pre-diabetes." (PMID 28258520, 2017). "In age and sex adjusted model, EN-RAGE, IL13, CFH, IL18 and CRP were associated with incident pre-diabetes." (PMID 28258520, 2017). "Further, a significantly high C3 deposition in the capillary wall along with thickening of basement membranes and co-localization of CFH expression with CD11b+ve activated microglial cells in diabetic retina suggested microglia as a source of CFH in diabetic retina." (PMID 32117292, 2020). "We postulated that activation of the complement system, possibly mediated by genetically determined reduced CFH bioavailability, could play a central role in the onset and progression of renal and vascular complications of diabetes." (PMID 31428128, 2019).